TREM2 (triggering receptor expressed on myeloid cells 2)
Diseases named in the same sentence as TREM2 in open-access papers (continued):
Sharing a sentence is not in itself a finding about the gene and the disease.
infection (continued). "Our results showed that transcription of TREM2 was two times higher at 3 days post-infection (dpi), three times higher at 9 dpi, and eight times higher at 30 dpi, compared to uninfected conditions." (PMID 39497817, 2024). "During infection, TREM2 inhibits TLR responses and reduces pro-inflammatory cytokines and chemokines, as well as recruitment of neutrophils." (PMID 38236825, 2024). "TREM2 acts as a triggering receptor in SARS-CoV-2 infection and is therefore associated with infection susceptibility and severity." (PMID 37962454, 2024). "Overall, these studies support the possibility that TREM2 regulates the anti-inflammatory phenotype of immune cells during infection and mitigates inflammatory tissue damage." (PMID 38236825, 2024). "We first measured TREM2 expression in the livers of S. japonicum‐infected mice and found that Trem2 mRNA expression was significantly upregulated at 9 and 12 weeks post‐infection compared to uninfected controls (**p < 0.01)." (PMID 37430471, 2023). "Ankita identified that infection of macrophages by Mtb is recognized by TREM2 and upregulates TREM2 expression through activation of the STING pathway, which, in turn, increases IL-10 and IFN-β expression." (PMID 38203570, 2023). "Our analysis showed that ΔsteE STm infection led to lower frequencies of RPM, Nos2+, Vcam1+, and Trem2+ MΦs compared to WT STm infection." (PMID 36608122, 2023). "We, therefore, assessed how Trem2 and Tyrobp mRNA levels in brains and SCs are altered by infection, and correlate with BMDM accumulation." (PMID 36333761, 2022). "Studies have found TREM2 to be essential for intracellular bacterial killing by enhancing ROS production in the context of Salmonella Typhimurium and P. aeruginosa infection." (PMID 35924849, 2022). "Expression of Lpl, Fn1 and Cd36 were downregulated in both microglia and BMDM from Trem2−/− mice relative to WT mice overtime after infection." (PMID 36333761, 2022). "BMDM recruited to SCs in response to infection highly upregulated Trem2 mRNA compared to microglia coincident with viral control." (PMID 36333761, 2022). "For example, Trem2 facilitates macrophage infection by porcine reproductive and respiratory syndrome virus (PRRSV) and suppresses a protective proinflammatory response." (PMID 36333761, 2022). "This includes the upregulation of gene programmes involved in other neurodegenerative disorders, such as Apoe, Aif1, Cst7, Itgax, Tyrobp, and Trem2 at the point of infection in which clinical symptoms are detected." (PMID 36180478, 2022). "Our data reveal an essential role of Trem2 in the removal of damaged myelin induced by neurotropic MHV–JHM infection." (PMID 36333761, 2022). "In the present study, we demonstrate that M. tuberculosis binds to human TREM2 and that infection induces an upregulation of this receptor in human macrophages through a mechanism dependent on STING (the stimulator of interferon genes)." (PMID 35924849, 2022). "In vivo infection of CD4–TREM-2 conditional knockout mice with murine coronavirus mouse hepatitis virus A-59 showed that intrinsic TREM-2 in T cells enhanced TH1 response and viral clearance, thus aggravating lung destruction." (PMID 34878838, 2021). "The lipid sensing role of TREM2 has been shown as part of the microglia response but also during infection, as TREM2 is capable of recognizing mycobacterial cell-wall mycolic acid (MA)-containing lipids." (PMID 34794433, 2021). "We used a TREM-2 cKO mouse model of MHV-A59 infection to show that intrinsic TREM-2 in T cell promoted viral clearance and alleviated the destruction of lung." (PMID 34878838, 2021). "First, the kinetics of TREM2 expression in PAMs were analyzed by western blot at various hours post-infection (hpi) or multiplicities of infection (MOIs) following PRRSV infection." (PMID 32401783, 2020). "Next, after PAMs were infected with PRRSV following TREM2 knockdown, we detected the transcription of proinflammatory cytokines at the early stage of infection." (PMID 32401783, 2020).
infection (continued). "Accordingly, we performed a cell fractionation assay and found that nuclear accumulation of endogenous p65, measured following infection, occurred at earlier time points and to a greater magnitude in TREM2-silenced PAMs, as compared with controls." (PMID 32401783, 2020). "We also performed a metabolic profiling of Trem2−/− mice on day 8 post infection and found significant changes in the lipid profiles compared to WT mice, likely reflecting the extent of pathology." (PMID 28900132, 2017). "We also profiled γ/δ T cells, NK cells, NKT cells, neutrophils and macrophages in spleen and liver of WT and Trem2−/− mice upon infection by flow cytometry." (PMID 28900132, 2017). "This analysis revealed largely comparable numbers of cell populations albeit we noticed an increase of NK and NKT cells in Trem2−/− mice compared to WT mice on day 4 post infection." (PMID 28900132, 2017). "During infection, triggering receptor expressed on myeloid cells-2 (TREM-2) restrains dendritic cells (DCs) and macrophages (MΦs) phagocytosis, as well as reduces pro-inflammatory cytokines release through DNAX-activation protein 12 (DAP12) signaling." (PMID 27102437, 2016). "We observed increased TREM-1 and TREM-2 expression during experimental melioidosis, both at the local site of infection and systemically." (PMID 27253382, 2016). "To evaluate the role of TREM-2 in the systemic inflammatory response, we determined plasma cytokine levels 72h post-infection with B. pseudomallei." (PMID 27253382, 2016). "Relative to WT mice, Trem2-/- mice displayed strongly reduced bacterial loads both at the primary site of infection (P<0.01 for lung and BALF) as well as in distant organs and the systemic compartment (P<0.01 for blood and spleen)." (PMID 27253382, 2016). "SA2 infection induced expression of genes like Trem2 (triggering receptor expressed on myeloid cells), FERT2 (Fer tyrosine kinase-2) that will suppress inflammatory response." (PMID 25075227, 2014). "Together, TREM-2 was abundantly expressed within healthy lungs and further induced upon infection with S. pneumoniae." (PMID 24945405, 2014). "We then sought to determine pulmonary TREM-2 expression upon S. pneumoniae infection and found a time dependent upregulation in whole lung transcript levels, with highest expression 48 h post infection." (PMID 24945405, 2014). "Notably, in vitro infection studies revealed that TREM2 upregulation followed a temporal pattern parallel to M2 macrophage marker expression." (PMID 42291322, 2026). "Key findings are that the deletion of Trem2 has no impact on PrPd deposition after infection of the CNS with prions but that neuronal loss and vacuolation were increased in susceptible brain regions." (PMID 40400621, 2025). "Moreover, it has been documented that TREM2 is abundantly expressed in CD4+ T cells amidst infection and inflammation." (PMID 40552184, 2025). "The absence of TREM2 is intricately linked to a diminished capacity for bacterial clearance and an escalated vulnerability to infection, thereby underscoring its protective essence within macrophage functionality." (PMID 40552184, 2025). "However, BMDM polarized into M2, and infected with B. abortus had significantly increased TREM2 mRNA and protein levels at 24 h and 48 h after infection." (PMID 39497817, 2024). "Increasing TREM2 expression in liver macrophages may improve the prognosis of mice with severe infection by improving the liver energy supply." (PMID 38236825, 2024). "It is also worth investigating whether lysosomes regulated by TREM2 during infection play a role in the TREM2 antimicrobial response in the future." (PMID 38236825, 2024). "To address whether M. tuberculosis-induced upregulation of TREM2 expression impacts the outcome of infection, we investigated the intracellular M. tuberculosis burden in macrophages lacking or overexpressing TREM2." (PMID 35924849, 2022).
infection (continued). "BMDM, which are rapidly recruited to the CNS during MHV–JHM infection may thus also contribute to Trem2 functions, specifically phagocytosis of damaged myelin." (PMID 36333761, 2022). "Using neurotropic MHV–JHM infection as a model of acute encephalomyelitis resolving into a persistent infection associated with demyelination, our studies showed that Trem2 deficiency did not affect viral control or establishment of persistence." (PMID 36333761, 2022). "Interestingly, WT microglia dramatically increased Lpl, Fn1 and Cd36 expression after infection, whereas Trem2 ablation resulted in the complete failure to upregulate these genes in microglia." (PMID 36333761, 2022). "Analyses of the cytokine production (MCP-1 and TNF), macrophage infiltration (estimated by Adgre1 (F4/80) expression), and Nos2 (iNOS) induction in the infected lungs detected a higher expression of Ccl2 (MCP-1), Adgre1, and Nos2 in Trem2−/− mice than in WT mice at day 3 after infection." (PMID 33863908, 2021). "Upregulation of TREM2 early in infection could be a double-edged sword for the host as PRRSV infects macrophages." (PMID 33187194, 2020). "Additionally, NF-κB mRNA was induced as early as 6 hpi in TREM2-silenced PAMs and maintained a high transcription level throughout the early stage of infection." (PMID 32401783, 2020). "The cytoplasmic tail domain of TREM2 interacted with PRRSV Nsp2 to promote infection." (PMID 32401783, 2020). "Meanwhile, TREM2 knockdown enhanced the mRNA expression of TLR4 at the early stage of infection." (PMID 32401783, 2020). "We demonstrated that the cytoplasmic tail of TREM2 interacts with PRRSV Nsp2 to promote infection." (PMID 32401783, 2020). "TREM2 is involved in the malaria liver stage infection through the activation of Kupffer cells." (PMID 32401783, 2020). "In contrast to the WT group, the TREM2-deficient corneas showed more intense TUNEL-positive staining in the cornea stroma (magnification = 200×, 400×) after infection, suggesting that TREM2 suppressed the death of the infiltrating cells in P. aeruginosa-infected corneas." (PMID 29887864, 2018). "Finally, Tyrobp mRNA encoding for the TREM2 adaptor DAP12 and known to regulate microglia phagocytic functions, was downregulated in BMDM throughout infection, but specifically upregulated within microglia at days 10 and 14 p.i.." (PMID 29942315, 2018). "However, many other studies suggest that TREM2, in addition to its important role in the CNS, plays an immunomodulatory role during infection." (PMID 28900132, 2017). "We also detected reduced levels of serum IFNα in Trem2−/− mice upon infection." (PMID 28900132, 2017). "72h post-infection 100% of WT but only 20% of Trem2-/- mice had become bacteraemic." (PMID 27253382, 2016). "Therefore, we determined the granulocyte influx into the pulmonary compartment by Ly6G-immunostaining in WT and Trem-2-/- mice 72h post-infection with B. pseudomallei." (PMID 27253382, 2016). "This hypothesis is also supported by our data that transfection of the miR-125b-5p prior to infection is associated with ERK activation, another marker of macrophage activation, which is consistent with the findings in TREM-2 knock-down macrophages." (PMID 27473222, 2016). "Interestingly, while microglia downregulated nominally phagocytic genes, Cd68, Mertk and Trem2, following infection, MG4 and MG5 upregulated the TAM receptor Axl which can recognize apoptotic and virus-infected cells expressing phosphatidylserine, potentially enhancing viral clearance." (PMID 37016414, 2023). "We measured the expression of TREM2 in peritoneal macrophages from mice infected with S. japonicum and found that the percentage of TREM2 positive F4/80 + CD11b + cells was enhanced at 6 weeks (p < 0.05), 9 weeks (p < 0.01) and 12 weeks (p < 0.001) post‐infection relative to uninfected controls." (PMID 37430471, 2023).
infection (continued). "Interestingly, L. monocytogenes infection only transiently and modestly induced TREM2 expression at early time points after infection, suggesting that additional mycobacterium-specific factors and/or unique host factors are likely required to trigger the upregulation of TREM2." (PMID 35924849, 2022). "However, it remained unclear whether TREM2 interacts with M. tuberculosis in human macrophages and if such interactions contribute to phagocytosis or an immunomodulatory role during infection." (PMID 35924849, 2022). "As expected, TREM2 expression in macrophages was continuously increased in PLF, liver, and lung after LPS injection or PA infection." (PMID 39405126, 2024). "TILT-322 infection of ovarian ascites samples led to downregulation of 14 differentially expressed genes (SLC26A4-AS1, APOE, TREM2, CD36, AC145676.1, VENTX, FP671120.4, AC007663.4, AC112220.2, C1QC, TEPP, AC027796.4, AC016026.1, and C1QA) in ascites samples." (PMID 38910324, 2024). "Elevated expression of multiple inflammatory genes, including IL6, TNF, IL10, and IL1B, were observed in the CD163+MRC1+TREM2 Mac and CD163+MRC1− subsets in both Cohort 1 and 2 after infection." (PMID 37024448, 2023). "Overall, the increased number of F4/80+ TREM2+ positive co‐staining cells in S. japonicum‐infected mouse livers suggests that TREM2 may be involved in the polarization of macrophages during the course of infection, potentially contributing to the M2 polarization of macrophages." (PMID 37430471, 2023). "Next, to investigate the relevance of this observation in vivo, we have intratracheally infected WT and Trem2−/− mice with M. bovis BCG, and examined the bacterial burden and inflammatory mediators in the infected lungs at days 3 and 14 after infection." (PMID 33863908, 2021). "Zhu and colleagues found that the infection of porcine reproductive and respiratory syndrome virus (PRRSV) induced Trem2 upregulation in porcine alveolar macrophage." (PMID 33557250, 2021). "Results showed an increased frequency of TREM-2+CD4+ T cells in the lungs and spleens of C57BL/6 mice after MHV-A59 infection." (PMID 34878838, 2021). "Microglial receptors such as toll-like receptors, Triggering receptor expressed on myeloid cells 2 (TREM-2), etc., receives the signals from the environment and activates microglia in response to infection or inflammation." (PMID 32944223, 2020). "To substantiate the finding that Trem-2-/- mice are protected during melioidosis, we determined bacterial loads in lung and BALF as well as in blood, liver and spleen 72h post-infection." (PMID 27253382, 2016). "This increase in pulmonary TREM-2 expression during infection most likely reflected the influx of TREM-2 expressing cells, since TREM-2 transcript levels on primary AM declined following S. pneumoniae treatment." (PMID 24945405, 2014). "Conversely, CpG sites related to Slc11a1, Havcr2, Ccl11, Ccl12, Sirt1, Ifng, Ccl3, Ror2, and Trem2 maintained lower methylation levels throughout the infection compared to noninfected samples." (PMID 40170749, 2025). "TREM2 acts as a trigger receptor and inflammatory modulator in SARS-CoV-2 infection; this activates the inflammatory pathway to promote viral clearance in the early stage of infection." (PMID 37962454, 2024). "Moreover, we found that T4SS is required for the upregulation of TREM2, as the ΔvirB2 mutant or inhibition of T4SS expression suppresses infection-triggered increases in TREM2 expression." (PMID 39497817, 2024). "Upon MHV–JHM infection, Trem2 and Tyrobp mRNA levels were not altered at days 5 and 7 post infection (pi), although BMDM constitute the most prominent brain infiltrating leukocyte population at this timepoint." (PMID 36333761, 2022). "Although apoptotic cells during MHV–JHM infection of WT mice are mainly lymphocytes, it remains to be identified whether microglia/BMDM or other cell types are indirectly affected by Trem2 ablation." (PMID 36333761, 2022).
infection (continued). "In this study, TREM2 knockdown in PAMs intensified the PRRSV-induced proinflammatory response and amplified the release of proinflammatory cytokines and type I interferons, particularly at the early stage of infection." (PMID 32401783, 2020). "We found that infection with LCMV perturbs the composition of circulating lipid species in wild type (WT) mice, which prompted us to investigate the role of the recently described lipid-sensing receptor TREM2." (PMID 28900132, 2017). "Gene expression of Trem2 also increased 3.44 fold at day 3 compared to day 1 post infection in our model, but we did not detect an increase of immunoglobulins." (PMID 23936388, 2013). "However, there was no change in TREM2 expression in the livers of Trem2−/− mice before or after infection." (PMID 37430471, 2023). "Furthermore, expression of Arg1 mRNA, which represents M2 macrophage polarization, did not increase with longer infection duration in Trem2−/− mice." (PMID 37430471, 2023). "In addition, WT BMDM also upregulated Lpl transcripts following infection, but transcriptional activation was inhibited in the absence of Trem2." (PMID 36333761, 2022). "Analysis of our published SC derived microglia and BMDM nCounter Nanostring mRNA expression data throughout MHV–JHM infection revealed that Trem2 mRNA levels in microglia were not substantially altered during acute infection, but slightly increased at day 14 pi coincident with demyelination." (PMID 36333761, 2022). "In addition, Trem2-/-, but not wildtype mice exhibited higher IL-6 following infection." (PMID 39250507, 2024). "The upregulation of TREM2 occurs 3 days postinfection and is only triggered by infection with live mycobacteria, as gentamicin-killed M. bovis BCG and M. tuberculosis failed to induce TREM2 expression." (PMID 35924849, 2022).